NOTCH1 (notch receptor 1)
Diseases named in the same sentence as NOTCH1 in open-access papers (continued):
Sharing a sentence is not in itself a finding about the gene and the disease.
tumor (continued). "In contrast, DAOY-NERT2HIF2α−/− cells exhibited more rapid tumor growth than the control cells, which was partially reduced by Notch1 ICD expression by tamoxifen." (PMID 29993038, 2018). "In contrast, Notch1 overexpressing tumor showed a reduction of IFN-γ secretion in homogenate supernatant." (PMID 29301578, 2018). "POFUT1, NOTCH1 and POFUT1/NOTCH1 high expressions are significantly associated with the tumor issue site, preferentially overexpressed in rectum tissue (84.6%, 84%, 76.1%, respectively)." (PMID 30380753, 2018). "We found higher frequencies of cells expressing surface NOTCH1 in tumor cells isolated from spinal metastases compared with tumor cells from the primary tumor sites in all xenografts analyzed." (PMID 30297829, 2018). "To examine the role of Notch1 in tumor growth, we stably silenced Notch1 expression using shRNA in B16 tumor cells." (PMID 29301578, 2018). "A U87-implanted intracranial model was used to study the effect of miR-139-5p on tumour growth and Notch1 suppression efficacy or EMT reversion." (PMID 30170559, 2018). "After selection, five miRNAs were characterized (miR-29, miR-31, miR-150, miR-155, and miR-200), all with tumor-suppressive effects in NOTCH1-driven T-ALL model." (PMID 29435192, 2018). "Collectively, these findings underscore the important role of intestinal epithelial Notch-1 in determining dissemination of tumor cells and invasion." (PMID 30323897, 2018). "Reduction in NOTCH1/2 levels was found to be mediated in part by tumor-infiltrating myeloid-derived suppressor cells (MDSCs)." (PMID 30967879, 2018). "Our results showed low TGF-β1 secretion and rare infiltration of Treg cells and MDSCs in tumor microenvironment after Notch1 knocking down." (PMID 29301578, 2018). "Notch1 can also enhance EMT during tumor progression via crosstalk with several regulators and growth factors relevant to EMT." (PMID 29321718, 2018). "The tumor weight of miR-3178 and miR-3178/p-NC was significantly lower than that with m-NC and miR-3178/p-Notch1." (PMID 30333478, 2018). "To investigate the mechanism how CTLs were inhibited through Notch1 in the tumor microenvironment, we assessed the percentage of MDSCs and Tregs in tumor-DLNs of either Notch1 knocked down or knocked in cells." (PMID 29301578, 2018). "It was also shown that the oncogenic NOTCH1/MYC pathway inhibited the expression of tumor suppressor miRNAs, including miR-31, miR-150, and miR-155." (PMID 29435192, 2018). "Our study indicates that VJ effectively suppresses AKT-induced tumor growth and inhibits Notch1 and AKT-mediated EMT in colon cancer." (PMID 30038258, 2018). "To investigate the effect of Notch1 in tumor tissue on local anti-tumor immunity, we analyzed the immune status in the tumor microenvironment of B16 tumor-bearing mice." (PMID 29301578, 2018). "Cross-talking with many other critical cancer genes and pathways, NOTCH1 is involved in multifaceted regulation of cell survival, proliferation, tumor angiogenesis, and metastasis." (PMID 30181806, 2018). "Consistently, Notch1 blockade results in downregulated secretion of VEGF associated with a reduction of tumor angiogenesis and tumor cell invasive abilities." (PMID 30154786, 2018). "Others have demonstrated a role for Notch1 of tumor dormancy in the bone marrow microenvironment, instigating metastases, through a Notch1/STAT3/LIFR signaling axis." (PMID 30515368, 2018).
tumor (continued). "In summary, our study demonstrates that Notch1 expression is low in AKT/Yap tumor cells, and ablation of Notch1 in hepatocytes delays ICC tumorigenesis." (PMID 29545603, 2018). "Genes such as CFLAR, EP300, GBP2, HEYL, KLF7, NOTCH1 or POFUT showed a similar correlation with NUMB or NUMBL in the three tumor types considered." (PMID 29507685, 2018). "In the TNBC UM-PE13 xenograft, blockage of DLL-4, decreasing Notch1 signaling, resulted in delayed tumor regrowth after paclitaxel treatment, with additionally decreasing the CSC frequency." (PMID 30515368, 2018). "Much progress has been made in elucidation of the oncogenic or tumor suppressor role of miRNAs in NOTCH1-driven T-ALL with this model." (PMID 29435192, 2018). "To further confirm the effect of Notch1 on tumor growth, we generated a B16 cell line that highly expressed Notch1 (B16-Notch1) by lentivirus expression vector." (PMID 29301578, 2018). "When B16 cells transfected with a control vector (B16-GFP) and B16-Notch1 cells were inoculated into immunocompetent C57BL/6 mice, overexpression of Notch1 significantly increased tumor burden and shortened mice survival time." (PMID 29301578, 2018). "Knocking down Notch1 significantly retarded tumor growth in C57BL/6 mice and extended mice survival time." (PMID 29301578, 2018). "In our study, miR-3178 significantly reduced the expression of Notch1, and the restored expression of Notch1 attenuated the inhibition of miR-3178 on tumor proliferation and metastasis." (PMID 30333478, 2018). "Elegant studies have shown that Notch is a central mediator of tumor-induced T-cell anergy and that activation of Notch1 in CD8 T-cells enhances cancer immunotherapy." (PMID 29915603, 2018). "CBL0137 can activate NOTCH1 and inhibit the self-renewal of CSCs/TICs, thereby facilitating the enhanced prevention of therapeutic resistance and tumor progression." (PMID 30581774, 2018). "Specifically, Notch2 is strongly expressed in ICC cells, whereas Notch1 is predominantly expressed in the cells of the tumor microenvironment." (PMID 29545603, 2018). "In contrast, concomitant activation of K-Ras and Notch1 significantly decreased the latency of tumor development, leading to iCCA formation by ~11 weeks post-hydrodynamic transfection." (PMID 29348467, 2018). "17β-estradiol treatment was also able to increase tumor microvessels in vivo, which correlated with Notch1 expression." (PMID 30515368, 2018). "Notch-1 immunopositivity is observed in cell processes of undefined cells distributed in the tumour border and around large SAs of stages II–III." (PMID 30140373, 2018). "It has been verified that abnormal Notch1 plays an important role in regulation of tumor cell proliferation and apoptosis." (PMID 30156609, 2018). "The ability of VJ to overcome AKT/Notch1 overexpression and to serve as a potential inhibitor of cancer progression was evident in vivo results, wherein cell proliferation and tumor burden were significantly reduced in the AKT/HCT 116 xenografts." (PMID 30038258, 2018). "The stemness‐associated genes were analysed using RT‐qPCR, and the results showed that the mRNA levels of Nanog, Sox2, Oct4, CD44, CD133, ABCB1, ABCC1, ABCG2 and Notch1 were significantly increased in RCC tumour spheres compared with parental cells." (PMID 30246456, 2018). "Various tumour biomarkers that associate with outcome of CRC patients treated with a bevacizumab-based therapy have been reported, such as NOTCH1 which associates with poorer survival." (PMID 29535825, 2018).
tumor (continued). "In support, the immunohistochemical analysis of the tumor samples showed a higher expression level of NF-κB, Notch1 and WNT1 in DLD-1R tumors than its DLD-1 parental samples; a reverse observation was made in E-cadherin expression." (PMID 30005681, 2018). "Recent data also demonstrates that inhibition of Notch-1/Jagged1 by alteration of microRNA miR-34a prevents tumor cell invasion and metastasis in CRC cell lines." (PMID 30323897, 2018). "In the present study, elevated Notch1 mRNA expression was found in both peripheral and tumor-resident CD4+ T cells in lung adenocarconoma patients." (PMID 30473538, 2018). "A volume of reports have demonstrated the role of NOTCH1 acting as oncogene but also tumor suppressor genetically in different cancers." (PMID 29665790, 2018). "Notch1 was upregulated in classical and proneural subtypes of GBM, and associated with tumour grade." (PMID 30170559, 2018). "In a mouse model of lung cancer, Notch1 promotes tumor initiation and progression, whereas Notch2 has tumor suppressor functions." (PMID 29177029, 2017). "The cannabinoid anti-tumor activity also acted through Notch-1 signalling pathway inactivation and MMP-2 down regulation." (PMID 28903355, 2017). "Our findings suggest that reduced tumor xenograft growth was at least partially attributed to impaired angiogenesis as a result of Notch1 downregulation." (PMID 29152141, 2017). "In accordance, Notch activation was evidenced in AtT20 tumor corticotropes, with higher levels of NOTCH1-3 active domains, Jagged1 and Hes1 compared to normal pituitary." (PMID 28915655, 2017). "The activation of MMP-9/Notch signalling was associated with increased CRC cells invasiveness, suggesting a tumor-prone role of Notch1 signalling in sporadic CRC." (PMID 28785079, 2017). "Tumor xenografts composed of P. gingivalis–infected OSCC cells demonstrated a higher resistance to Taxol through Notch1 activation, as compared with uninfected cells." (PMID 28388583, 2017). "Similar to the analysis comparing primary and recurrent tumors, the mutation status differed among tumor regions, even that of major driver genes such as CIC, FUBP1, PTEN, and NOTCH1." (PMID 28270234, 2017). "In this region Notch1 and Notch3 was also ectopically expressed, appearing diffusely in the tumor epithelium." (PMID 28086833, 2017). "Our findings are consistent with previous reports regarding the tumor suppressive role of Notch1 in SCLC." (PMID 28060745, 2017). "High expression of Notch1 in HepG2 cells promoted the xenograft growth in nude mice, with more VM formation in the tumor speciemens." (PMID 27705934, 2017). "This shows that tumour endothelial FABP4 expression is induced by activation of NOTCH1 signalling, and can be targeted by inhibition of VEGFA and NOTCH1 signalling." (PMID 27568980, 2017). "Several evidence reported that in vivo hypoxia upregulated expression of Dll4, Jagged1, Notch1, Notch4, Hes1, and Hey which in turn promoted tumor angiogenesis." (PMID 28157712, 2017). "Previously we have shown that FABP4 in endothelial cells is induced by the NOTCH1 signalling pathway, the latter of which is involved in mechanisms of resistance to antiangiogenic tumour therapy." (PMID 27568980, 2017).
tumor (continued). "Here, we studied the expression of Notch1, Jagged1 and NICD in epithelial ovarian carcinoma tissues, analyzed the clinical significance and explored the potential anti-tumour effect of γ-secretase in epithelial ovarian carcinoma cell lines." (PMID 28030808, 2017). "In conclusion, Notch1 ablation inhibited GBM cell proliferation and neovascularization and radiosensitized GBM cells and xenografts, suggesting a pivotal role of Notch1 in tumor growth, angiogenesis, and radioresistance in GBM." (PMID 29152141, 2017). "In the present study, we identified that the expression of Notch1 protein went lower in HCC cancer tissues compared with that in non-tumor tissues." (PMID 28507277, 2017). "Notch1 function is highly context-dependent, and can either be oncogenic or have a tumor suppressor function." (PMID 27861153, 2017). "Notch1 expression has been found to be positively correlated with tumor progression and poor survival of malignant glioma patients." (PMID 29152141, 2017). "Notch1 is a master regulator of cell growth and differentiation across many cell types, and perturbations in Notch signaling can confer either oncogenic or tumor suppressor effects on a cell, depending on its context." (PMID 29117186, 2017). "Although CCR7 regulates Notch1 activation in MMTV-PyMT tumor cells, the two pathways likely cooperate to promote CSC activity." (PMID 28137279, 2017). "We suspected that TGFβ influences Notch1-mediated tumor promotion and EMT since the TGFβ target gene PAI1 was upregulated in CD44H cells in tumors." (PMID 29170450, 2017). "In conclusion, our results demonstrate that in U-87 MG cells, KMT2A positively regulates NOTCH1 and NOTCH3, and this KMT2A–NOTCH1/3 cascade is essential for the inhibition of tumor cell proliferation." (PMID 28968975, 2017). "Other report showed that Jagged1 is overexpressed in the tumor tissue with concomitant Notch1 and 2 activation." (PMID 28086833, 2017). "Here, we report that AP‐1 acts as a tumor suppressor by inducing Notch1 in NE cancer cells that are treated with HDACi." (PMID 28776955, 2017). "The activation of the Notch1 pathway goes in parallel with exacerbated amounts of ICN1 in the tumor cells." (PMID 29136506, 2017). "NOTCH-1 is believed to play a role in regulating normal cell differentiation and has dual functions with both oncogenic and tumor suppressor activity." (PMID 31093353, 2017). "As we know, ITCH is an anti-cancer protein targeting p63, p73, and Notch1 gene and usually involve in tumor formation and chemosensitivity." (PMID 28279183, 2017). "Concurrently, TGFβ drives Notch1-mediated EMT to generate tumor initiating cells characterized by high CD44 expression." (PMID 29170450, 2017). "Activation of Notch1 together with Wnt signalling seems to be essential to trigger CRC initiation by maintaining the self-renewal of tumor stem cells." (PMID 28086833, 2017). "Given the growing evidence that γ‐secretase cleavage regulates signaling from numerous type 1 membrane proteins, the probability that extent of NOTCH1 inhibition is the only determinant of anti‐tumor activity is small." (PMID 28539479, 2017). "NOTCH1, CDKN2A, FBXW7, FAT1, and ZNF750 were considered as tumor suppressors and showed recurrent inactivating mutations." (PMID 29348864, 2017). "When comparing lean and obese in the type I tumor only, significantly higher expression in Notch1, Notch4, DLL4, OB-R, and IL-1R tI were found in obese patients (p < 0.05)." (PMID 28659656, 2017). "CRISPR/Cas9-mediated NOTCH1 deletion dramatically impaired tumor formation by TE11 cells in immunodeficient mice, supporting a role for Notch1 in tumor initiation as well." (PMID 29170450, 2017).
tumor (continued). "In the present study, all of the 44 tumor specimens were found to have moderate to strong positive Notch1 and Hes1 staining, while 27 out of 44 matched paraneoplastic specimens were identified with only slight to moderate expression." (PMID 27705934, 2017). "We found that NOTCH1 is significantly correlated with tumour stage (Fisher’s exact test, p < 0.001) and lymph node metastasis (Fisher’s exact test, p < 0.001), consistent with previous studies." (PMID 29127303, 2017). "High expression of Notch1 in HepG2 promoted xenograft growth in nude mice, with abundant VM formation in the tumor samples." (PMID 27705934, 2017). "In summary, our findings suggest a pivotal role of Notch1 in tumor growth, angiogenesis, and radioresistance in GBM." (PMID 29152141, 2017). "It has been reported that PDGF-D increases tumor growth and aggressiveness by activating Notch1 and NF-κB in human pancreatic and breast cancer." (PMID 28035069, 2017). "In vivo, we found that increased NOTCH1 signalling in tumour xenografts led to increased expression of endothelial FABP4 that decreased when NOTCH1 and VEGFA inhibitors were used in combination." (PMID 27568980, 2017). "Increasing reports demonstrated that deregulation of Notch1 signaling can be observed in diverse tumor types, such as cervical cancer." (PMID 28507277, 2017). "In considering both tumor and normal samples, miR-34a was inversely correlated with NOTCH1 (r = −0.563, P = 0.001), SLUG (r = −0.374, P = 0.009), ZEB1 (r = −0.505, P = 0.001), and ZEB2 (r = −0.317, P = 0.028) expressions." (PMID 28423483, 2017). "miR-326 is a recognized tumor-suppressing miRNA, in fact among its targets there are Gli2, Smo, Notch1, Notch2 and Nob1." (PMID 28716052, 2017). "In fact, Notch1 activation led to repression of neuroendocrine markers apoptosis induction and reduced tumor growth making it an interesting molecule for MTC therapy." (PMID 28122586, 2017). "The mRNA level of Notch1 signal pathway related facter were detected by RT-PCR; the expression of Notch1 signal pathway related facter in tumor tissue was detected by western blot." (PMID 28855037, 2017). "Our findings establish gal-3 as a molecular regulator of the JAG1/Notch-1 signaling pathway and have direct implications for the development of strategies aimed at controlling tumor angiogenesis." (PMID 28533486, 2017). "Despite the structural similarity, NOTCH1 exerts tumor suppressive whereas NOTCH2 exerts oncogenic actions via different downstream signaling targets in other malignancies." (PMID 29242529, 2017). "The IHC staining results revealed that activated Notch1 signaling was very robust in sh-Luc treated tumor tissue as compared to sh-ASPH treated cells, suggesting that targeting ASPH with shRNAs substantially inhibits Notch signaling and blunts CCA growth." (PMID 26954680, 2016). "Given the relatively high expression of Trib2 in developing T cells and its positive correlation with human T-ALL, we were surprised to find that Trib2 functioned as a tumor suppressor in our murine Notch1-induced T-ALL model." (PMID 27191957, 2016). "To evaluate the relevance of Notch1 signalling in Ptenpc−/− tumours, we generated prostate conditional knockout of both Pten and Notch1 in mice (hereafter referred as Ptenpc−/−; Notch1pc−/−)." (PMID 27941799, 2016). "In separate study, using HBx overexpressing non-tumor hepatic cell line L02 cell line, Notch1 was demonstrated to co-immunopricipitate with HBx and increasing activation of NF-κB activity in this cell line was shown to be dependent on HBx/Notch." (PMID 26766040, 2016).